HIF1A (hypoxia inducible factor 1 subunit alpha)
Diseases named in the same sentence as HIF1A in open-access papers (continued):
Sharing a sentence is not in itself a finding about the gene and the disease.
cancer (continued). "For example, HIF-1α upregulates the expression of vascular epidermal growth factors which stimulate angiogenesis in cancer." (PMID 28881698, 2017). "Another gene related with cancer is hif-1α, which has been identifiedas a key regulator of angiogenesis, inflammation and anaerobic metabolism." (PMID 28486571, 2017). "The HIF-1α and HIF-1β complex binds to the hypoxia-response element (HRE), thereby affecting various downstream genes associated with cancer cell angiogenesis, migration, and metastasis." (PMID 28257048, 2017). "Several growth factors, metabolites or activated oncogenes can induce HIF‐1α under non‐hypoxic conditions in numerous cancers." (PMID 28236660, 2017). "Based on this study, we attempted to establish a novel anti-cancer therapy using a specific HIF-1α inhibitor combined with GI to target hypoxic cancer cells in gastric tumours." (PMID 28978999, 2017). "In the present study, we generated a novel BiFC system that imaged real-time interaction between HIF-1α and SEPT9_i1 proteins in live cancer cells." (PMID 28380438, 2017). "It has been shown that HAF switches the hypoxic response of the cancer cell from HIF-1α-dependent to HIF-2α-dependent transcription and activates genes involved in invasion such as MMP9, PAI-1, and the stem cell factor OCT3/4." (PMID 28572533, 2017). "Conversely, in cancer cells exposed to hypoxia, pyruvate is shunted away from the mitochondria by HIF-1α-mediated PDK1 upregulation, which inhibits PDH activity." (PMID 28978999, 2017). "In solid tumor, hypoxia is a crucial microenvironmental stimuli that leads to significant up-regulation of hypoxia-inducible factor-1α (HIF-1α) in majority of human cancers." (PMID 29026004, 2017). "Next, to investigate the effect of hypoxia, a cancer microenvironment, we compared TrkB and HIF-1α expression in normoxic and hypoxic conditions." (PMID 28423707, 2017). "HIF-1α is undetectable in normal cells, but cancer cells frequently express HIF-1α to support their growth, angiogenesis, and high glycolysis (also known as the Warburg effect)." (PMID 29152137, 2017). "Hypoxia in early cancer transformation results in expression of hypoxia inducible factor 1 alpha (HIF-1α) activating pyruvate dehydrogenase kinase (PDK), a pyruvate dehydrogenase (PDH) inhibiting enzyme." (PMID 28591165, 2017). "Due to its role in supporting angiogenesis, the HIF-1α/VEGF signaling pathway is currently regarded as an outstanding pharmacological target to control aberrant vessel sprouting in cancer." (PMID 29240722, 2017). "SPHK-1 activates the AKT/GSK-3β signaling pathway, which is involved in the accumulation of HIF-1α levels under hypoxia in cancer." (PMID 28165392, 2017). "HIF-1α up-regulation under normoxic conditions has been noted with increasing frequency in many cancers." (PMID 28380438, 2017). "While HIF1α sustains proliferation in cancer cells, it upregulates glycolysis, and also specifically boosts IL-1β expression in response to LPS stimulation." (PMID 28233125, 2017). "It has been reported that the HIF-1α expression is highly correlated with the poor prognosis in cancer patients." (PMID 28710377, 2017). "Most studies have focused on HIF-1α when examining roles of HIFs in TRAIL-induced cancer cell death." (PMID 28476028, 2017). "In this study, we confirm that lactate stabilizes HIF-1α in HeLa and SiHa cancer cell lines, which is in good agreement with previous findings." (PMID 29100428, 2017). "K477R HIF-1α mutation and specific cancer-associated Parkin mutations largely abolish the functions of Parkin to ubiquitinate HIF-1α and inhibit cancer metastasis." (PMID 29180628, 2017). "HIF-1α accumulation leads to upregulation of genes that are involved in many aspects of cancer progression, including metabolic adaptation, apoptosis resistance, angiogenesis, lymphangiogenesis and metastasis." (PMID 28410190, 2017).
cancer (continued). "Hypoxia-inducible factor-1α (HIF-1α) is a transcription factor that regulates various biological processes under hypoxia in cancer, such as metabolism, cell proliferation and migration, angiogenesis and apoptosis." (PMID 28165392, 2017). "HIF-1α is a central regulator of the glycolysis energy metabolism involved in organ fibrosis, indicating a similarity between inflammation and cancer." (PMID 29186898, 2017). "The hypoxia-induced Epithelial to Mesenchymal Transition (EMT), driven by HIF1α, is known to be involved in cancer progression and metastasis." (PMID 28061476, 2017). "The data suggest that cancer-induced hepatic gluconeogenesis was attenuated when HIF-1α expression in cancer cells was decreased by emodin and rhein." (PMID 29152137, 2017). "To date, studies on HIF-2α in cancer cell death have frequently been performed with those of HIF-1α." (PMID 28476028, 2017). "Such adaptive survival response of cancer cells to hypoxic conditions is mainly mediated by the transcription factor, hypoxia-induced factor-1α (HIF-1α)." (PMID 29162839, 2017). "Nevertheless, the previous data supports our findings that conditions that intermittently increase HIF-1α, such as IH, have long-lasting effects on subsequent malignant tumor progression in vivo." (PMID 28977888, 2017). "Overexpression of HIF-1α is involved in the activation of multiple target genes crucial in cancer biology, including erythropoiesis, angiogenesis, glucose metabolism, cell proliferation, survival, and apoptosis." (PMID 28512631, 2017). "Many studies have proved that HIF-1α plays an important role in increasing radioresistance of cancer cells via the regulation of glucose metabolism, the cell cycle, and radiation-induced cell apoptosis." (PMID 28810896, 2017). "We also revealed that the miR-1/Smad3 axis regulated cancer cell metabolism by targeting HIF-1α or by an HIF-1α-dependent mechanism including a positive loop by which Smad3 interacts with and regulates HIF-1α." (PMID 28471448, 2017). "HIF-1α, when stabilized by hypoxic conditions, mediates the response to hypoxia and upregulates many genes important for cancer development such as a vascular endothelial growth factor (VEGF) which promotes angiogenesis." (PMID 28165392, 2017). "STAT3 and HIF-1α, two major transcription factors that regulate VEGF, have been found to be consistently upregulated in various cancers including HCC and associated with poor clinical outcomes in patients." (PMID 28978924, 2017). "It has been shown that the expression of over 20 genes is directly regulated by HIF-1α; among these genes is NFκB1, a regulatory molecule of inflammation and cancer." (PMID 28512631, 2017). "A third major phenotype induced by inhibition of CDK4/6 in our cancer cell models is a limited response to hypoxia accompanied with downregulation of HIF‐1α, which can also be explained by the accumulation of MYC." (PMID 28978620, 2017). "Previous studies have reported that LPA upregulates HIF‐1α in numerous cancer types and we found a time‐dependent increase in HIF‐1α expression in response to LPA." (PMID 28236660, 2017). "HIF1α, is a critical mediator of cellular response to hypoxia and therefore has been found to be involved in cancer progression and metastasis." (PMID 28754121, 2017). "Initial reports found NHE1 expression to be increased in a HIF-1α-dependent manner in pulmonary arterial myocytes, whereas a later report in a wide array of cancer cell lines found NHE1 expression to be either downregulated or unaffected by hypoxia." (PMID 28806945, 2017). "Although mechanisms balancing oncometabolite concentrations represent intriguing therapeutic targets, their successful manipulation to fight cancer is still to be optimized, most likely due to the complexity of oncometabolite-mediated HIF-1α regulation." (PMID 29230384, 2017).
cancer (continued). "In this context, three major pro-survival pathways, namely ERK/MAPK, JAK/STAT, and PI3K/Akt/mTOR, concur to increase transcription and translation of HIF1A, especially in cancer." (PMID 29230384, 2017). "PX-478, noscapine, and phenethyl isothiocyanate (PEICT) inhibited HIF-1α expression in different cancer cells." (PMID 29152137, 2017). "Hypoxia-inducible factor-1α (HIF-1α) is a trans-cription factor normally regulated by oxygen concentration but is often overexpressed in solid tumors such as cancers of the colon, breast, pancreas, kidney, prostate and bladder." (PMID 29137361, 2017). "In osteosarcoma, for example, Hif-1α accumulation help cancer cells adapt to and survive in hypoxic conditions, decreased overall survival and disease-free survival." (PMID 28424584, 2017). "HIF-1α and HIF-2α are both key mediators of the response of hypoxic cancer cells to low O2 conditions; HIF-1α responds to acute hypoxic conditions, while HIF-2α accumulates over time." (PMID 28476026, 2017). "In certain cancer cells that exhibit Warburg metabolism, inhibition of PHDs can lead to HIF1α stabilization under normoxic conditions." (PMID 28233125, 2017). "pylori-mediated gastric carcinogenesis and a possible target for cancer prevention via inhibition of HIF-1α." (PMID 29108235, 2017). "Mechanistic studies demonstrated that HSP90-stabilized STK33 interacts with and regulates hypoxia-driven accumulation and activation of HIF-1α as well as secretion of VEGF-A in hypoxic cancer cells." (PMID 29100402, 2017). "Western blot analysis confirmed the stabilization of HIF-1α in various cancer cell lines exposed for eight hours to low oxygen conditions." (PMID 29100402, 2017). "HIF-1α is increasingly recognized as playing broad and critical roles in normal development, postnatal physiology, cancer and many other diseases." (PMID 28060721, 2017). "The importance of hypoxia-independent nuclear HIF-1α expression has also been reported in various malignant tumors." (PMID 28558056, 2017). "In our study, HIF1A staining was detected in both nuclei and cytoplasms of cancer and normal tissues, and nuclear HIF1A staining was significantly increased in cancer compared with normal controls." (PMID 27902480, 2017). "A number of pathways are involved in cancer signaling, and show overlap with the oxidative stress signaling pathway (e.g. HIF1-α, NO, NRF2, iNOS)." (PMID 28768896, 2017). "KEGG pathway analysis of the NRF2-KD microarray data identified HIF-1α in two major pathways: the thyroid hormone signaling pathway and proteoglycans in cancer." (PMID 29050246, 2017). "We used YFP-based BiFC methodology in order to study the interaction between HIF-1α and SEPT9_i1 in live cancer cells." (PMID 28380438, 2017). "HIF-1α constitutively expresses independently of oxygen level through various signaling pathways in cancer." (PMID 29158891, 2017). "High HIF-1α levels strongly correlate with cancer progression and hypoxia-mediated sorafenib resistance." (PMID 29207653, 2017). "Metformins’ ability to reduce the expression of markers of aggressive cancer was not limited to drug resistant cell populations, as metformin also prevented the expression of HIF1α following exposure to hypoxia." (PMID 29211738, 2017). "Conversely, in cancer cells facing hypoxia, it is plausible that α-KG conversion into (L)-2-HG most likely helps in reducing the energetic demand while promoting HIF1α stabilization for hypoxic adaptation." (PMID 28184304, 2017). "Our findings suggest that GATA3 stabilizes HIF-1α to enhance cancer invasiveness under hypoxia and support the GATA3/HIF-1α axis as a potential therapeutic target for cancer treatment." (PMID 28263977, 2017). "When MiaPaCa2 cells were implanted in athymic mice, emodin and rhein inhibited cancer-cell growth and HIF-1α expression." (PMID 29152137, 2017). "Because HIF-1α is an attractive target for the development of cancer therapeutics, we screened small molecules to find HIF-1α inhibitors." (PMID 27999195, 2017).
cancer (continued). "This is the first report describing epigenetic regulation of chromosomal HIF-1α turnover in gene activation that bears important implication in cancer therapy." (PMID 28883660, 2017). "We demonstrate that effective cancer cell death induced by FQ involves several factors including negative regulation of Akt kinase and HIF-1α, mitochondrial impairments, inhibition of autophagic-lysosomal function and LMP." (PMID 29162859, 2017). "Particularly, FABP7, involved in fatty acids uptake, is induced by HIF-1α, leading to the accumulation of LDs and contributing to cancer cell growth." (PMID 29312541, 2017). "HappMolitoris, et. al found that inhibition of HIF-1α degradation unmasks estradiol induction of VEGF expression in ECC-1 cancer cells in vitro." (PMID 28060721, 2017). "Recent study indicated that CDC25A, a critical cell cycle gene, is responsive to cellular hypoxia in human cancer, and HIF-1α-Myc pathway is also involved in the hypoxic downregulation of CDC25A." (PMID 29088751, 2017). "Hif-1α-mediated hypoxia adaption has been used frequently to explain the survival advantage of cancer cells under hypoxic conditions." (PMID 28705232, 2017). "Cells classically respond to hypoxia by activating the hypoxia-inducible transcription factors HIF1α and HIF2α, which induce changes in the gene expression of cancer cells." (PMID 29145444, 2017). "In the present study, we evaluated the inhibitory effects of vanillin on hypoxia-inducible factor (HIF)-1α accumulation and cancer cell motility under hypoxia by abrogating STAT3-mediated HIF1A mRNA expression." (PMID 28257048, 2017). "Our results showed that specific inhibition of the HIF1α activities almost completely reversed the increased expression of VEGF-A in 3D cultured cancer cells (2D, 1.1610 ± 0.0384; 3D, 2.3220 ± 0.0383; 3D + HIF1α inhibitor, 1.0010 ± 0.0386)." (PMID 29200966, 2017). "The biological responses of these siRNA-SWCNT complexes were investigated using various types of cancer cells, and the results showed that the complexes strongly inhibited cellular HIF-1α activity." (PMID 30970690, 2017). "We also found that LPA activation bio‐energetically reorients cancer cells towards a pseudo‐hypoxic condition through HIF‐1α induction." (PMID 28236660, 2017). "It has been reported that ROS are increased in hypoxic cancer cells, and HIF-1α induction plays an adaptive mechanism in controlling ROS generation via up-regulating genes involved in anaerobic glycolysis." (PMID 28978999, 2017). "During the metabolism transition, some factors such as HIF1α and ROS can also induce the malignant phenotype of cancers." (PMID 27911865, 2017). "HIF-1α activity leads to the upregulation of target genes, which advance cancer progression, angiogenesis, cell survival, and cell invasion." (PMID 28489881, 2017). "There is much evidence in developmental and cancer biology that HIF1α under hypoxic conditions coincides with the Wnt signaling pathway through β-catenin, which has substantial consequences for cellular fate and survival." (PMID 29422917, 2017). "Taken together, these results indicate that cancer-induced skeletal-muscle wasting was attenuated when HIF-1α expression in cancer cells was inhibited by emodin or rhein." (PMID 29152137, 2017). "It will be of interest to systemically investigate the impact of Parkin on HIF-1α levels and expression of HIF-1α downstream genes in different types of tissues and cancers." (PMID 29180628, 2017). "Cancer cells tend to enhance glucose uptake through HIF1a stabilization, promoting a GLUT1 increase." (PMID 28931650, 2017). "Overexpression of miR-622 efficiently reduces the HIF-1α level, thereby diminishing the migration and invasion abilities of cancer cells." (PMID 29383199, 2017). "Previous study showed that direct binding of HIF-1α to HRE site located -83 to -79 upstream of the transcription start site of TWIST1 gene upregulates Twist1 expression in various cancer cells." (PMID 28977889, 2017).
cancer (continued). "Based on these findings, our study provides an insight into a novel strategy targeting G6pdx and HIF-1α to overcome the UCHL1-dependent radioresistance of cancer cells." (PMID 28761052, 2017). "In this survey, It should be noted that HIF-1α positivity was considered specific only when the staining was found in cancer cell nuclei (arrows) while cytoplasmic staining was considered as non specific." (PMID 29312568, 2017). "Hif-1α is expressed in almost all cell types, including cancer cells, and it is recognized as a marker of poor survival in many solid tumors." (PMID 28424584, 2017). "Hypoxia and induction of HIF-1α have also been shown to expand the subpopulation of cancer stem-like cells and to increase resistance to therapies in various cancer types." (PMID 28468237, 2017). "HIF1α regulates the transcription of many genes involved in cancer pathogenesis and progression to more aggressive phenotypes." (PMID 28881665, 2017). "Stabilized HIF1α transcription factor plays an essential role in increasing glycolytic flux and decreasing mitochondrial biogenesis in cancer cells." (PMID 29212260, 2017). "Further, HIF-1α is also a crucial metabolic regulator in cancer cells and hypoxia is known to be related to radioresistance." (PMID 29163780, 2017). "Inhibition of HIF-1α in its pathways of synthesis, as well as in its pathway of degradation, would seem to make for a more efficient anti-cancer/anti-angiogenesis treatment." (PMID 27999195, 2017). "In this way, HIF-1α alter a number of metabolic pathways that play their role in cancer by providing energy to the cell for proliferation, growth, and survival." (PMID 29158891, 2017). "HIF-1α and SEPT9_i1 chimeras were expressed in cancer cells and screened for functional complementation." (PMID 28380438, 2017). "Recently, enhanced levels of HIF-1α protein have been detected in the cytoplasm and nuclei of 40% to 80% of human carcinoma cases." (PMID 28974006, 2017). "The HIF-1α transcription factor is abundantly expressed in most human carcinomas and their metastases and is the principal mediator of cellular adaptation to hypoxia." (PMID 28321776, 2017). "It has been reported that HIF-1α is a negative regulator of proliferation in chondrocytes and some cancer cells." (PMID 26841115, 2016). "Tenascin-C expression in cancer cells was associated with TAM population (p = 0.043), cancer recurrence (p = 0.014), and HIF1α expression in cancer cells (p = 0.004)." (PMID 26731558, 2016). "The expression of HIF-1α can be triggered by hypoxia, but also by pathological stress, such as inflammation and cancer." (PMID 26919249, 2016). "But at present, reports about monitoring the level of HIF-1α within blood in patients with cancer are still rare." (PMID 26853843, 2016). "Our studies suggest that NAF-1 is a major player in the metabolic pathways of cancer cells through its effects on cellular distribution of Fe ions, mitochondrial ROS formation, stabilization of HIF1α and induction of apoptosis." (PMID 26621032, 2016). "In fact, it is well known that HIF-1α expression is elevated in many cancers and is known to offer protection to cancer cells." (PMID 26791262, 2016). "Protein kinase CK2, a constitutive serine/threonine kinase which interestingly shows high CK2 activity in most human cancers can indirectly contribute to HIF-1α degradation." (PMID 26942179, 2016). "It well known that PI3K/Akt/mTOR signaling pathway mediates HIF-1α translation in various cancer cells." (PMID 27029070, 2016). "αHIF, an antisense RNA, can negatively adjust angiogenesis in cancer by regulating the expression of hypoxia-inducible factorα (HIF1α)." (PMID 27429196, 2016). "Potential insight again comes from cancer cell studies: ROS can stabilize HIF‐1α in an AKT‐independent manner and this effect is mediated by the oxidative consumption of ascorbate and Fe(II)." (PMID 26729005, 2016).